TNF (tumor necrosis factor)
Diseases named in the same sentence as TNF in open-access papers (continued):
Sharing a sentence is not in itself a finding about the gene and the disease.
colitis (continued). "MAM’s ability to mitigate colitis symptoms by reducing the levels of pro-inflammatory cytokines, particularly TNF-α, was demonstrated here through in vitro studies and in the literature." (PMID 41353317, 2025). "The symbiotic relationship between SP and EcN significantly reduces inflammatory markers such as TNF-α and IL-6, alleviates weight loss and colon shortening symptoms, and preserves intestinal epithelial integrity in a DSS-induced colitis mouse model." (PMID 40563329, 2025). "Findings from this study indicate that DSS-induced colitis in rats leads to significantly increased levels of IL-1β, IL-6, TNF-α, and MDA, along with a notable decrease in SOD levels, suggesting severe oxidative damage and inflammatory responses." (PMID 40417008, 2025). "As expected, the induction of acute colitis resulted in elevated levels of proinflammatory mediators such as TNF-α, PTX3, and PAF in plasma and TLR4 in colon tissue." (PMID 40572721, 2025). "In contrast, the colitis + suramin group exhibited significantly reduced colonic TNF-α levels (144.6 ± 4.3 pg/mg) compared to the colitis group (# p < 0.01), indicating effective suppression of local inflammation." (PMID 40428786, 2025). "After the onset of colitis, IL-10−/− mice have a higher secretion of inflammatory cytokines than wild-type mice, including TNF-α, IL-1β, IL-6, and IFN-γ." (PMID 40732952, 2025). "Modulating the Treg/Th2 response by decreasing proinflammatory cytokines such as TNFα, IL-6, IL-1β, IL-18, IL-22, IL-9 and increasing anti-inflammatory cytokines IL-10 and IL-4 in mice colitis model." (PMID 41208998, 2025). "Glycyrrhiza chalcone inhibited TNF-α, IL-1β, and IL-6 expressions in the colon tissue of mice with colitis." (PMID 41180229, 2025). "Plasma TNF-α concentrations were 19.55 ± 1.63 pg/mL in the control group and significantly elevated to 58.69 ± 3.96 pg/mL in the colitis + saline group (*** p < 0.001; p = 0.0001), indicating pronounced systemic inflammation." (PMID 40572721, 2025). "In the betanin supplementation groups, malondialdehyde, myeloperoxidase, TNF-α, IL-1β, mucosal damage, and cell infiltration scores were lower than in the colitis group, while GPx levels were higher." (PMID 41515203, 2025). "Given that PGRN interacts with the same receptor as TNFα, many studies have shown that PGRN can inhibit TNFα‐mediated diseases such as osteoarthritis, intervertebral disc degeneration and colitis." (PMID 39910695, 2025). "In a severe colitis rat model, AMSC transplantation improved colitis by inhibiting monocyte/macrophage activity, lowering inflammatory markers (TNF-α, IL-6, and IL-1β), and preventing NF-κB activation." (PMID 40076934, 2025). "Previous studies have supported this correlation, for instance, adherent-invasive E. coli can activate intestinal Th17 cell subsets, promoting the production of pro-inflammatory factors, such as IL-17 and TNF-α, thereby exacerbating colitis." (PMID 41476955, 2025). "In animal models of colitis, polyphenols and polysaccharides reduce inflammation by suppressing proinflammatory cytokines such as tumor necrosis factor (TNF)-α and interleukin (IL)-1β, increase Lactobacillus abundance, and decrease that of Bacteroides." (PMID 40001382, 2025). "Pre-treatment with recombinant TIMP-1 of mice with experimental colitis reduced the mucosal pathology while splenocytes from pretreated mice produced less TNF-α and more IL-10 than untreated mice following stimulation with anti-CD3." (PMID 40565065, 2025). "In response to DSS-induced colitis, pro-inflammatory cytokine levels (TNF-α, IL-1β, IL-6, IFN-γ, NF-κB, IL-17, and TGF-β) were significantly elevated in group 2, indicating their role in the pathogenesis of UC." (PMID 40502390, 2025). "In the DSS-induced colitis mouse model, we observed that P. scabiosaefolia effectively suppressed the secretion of TNF-α and IL-6 and downregulated their mRNA transcription levels." (PMID 40238255, 2025).
colitis (continued). "Blocking the NAD+ salvage pathway inhibited the secretion of IL‐1β, IL‐6, IL‐8, IL‐18, and TNF‐α in the serum and reduced the expression of TNF‐α in the tissues of F. nucleatum‐infected IFX‐treated DSS‐induced colitis mice." (PMID 39739648, 2025). "Analysis of liver tissue from DSS-induced colitis mice revealed elevated production of pro-inflammatory cytokines, such as IL-1β, IL-6, and TNF-α, along with upregulated LPS and MPO levels." (PMID 40725052, 2025). "To establish a well-defined pathophysiological context for investigating the anti-TNF-α mechanism of salidroside (Sal), we employed the LPS-Induced murine colitis model." (PMID 41296400, 2025). "Pro-inflammatory cytokines (IL-1β, IL-6, TNF-α) were markedly elevated in the Colitis group, while anti-inflammatory IL-10 was suppressed (p < 0.01)." (PMID 40574090, 2025). "As an emerging next-generation probiotic, PG can reduce the levels of pro-inflammatory cytokines IL-1β and TNF-α in mice with colitis, alleviate inflammatory damage, and maintain the integrity of the intestinal epithelium." (PMID 40400666, 2025). "Both E. coli and E. faecalis exhibited positive correlations with colon TNF-α, IL-6, and IL-17 levels, suggesting their potential role in promoting colitis development." (PMID 41476955, 2025). "Our results showed that prefeeding with B. velezensis MZ09 reduces the levels of the proinflammatory cytokines IL-6 and TNF-α in a DSS-induced colitis model, thus alleviating colonic damage." (PMID 40883849, 2025). "In animal models of colitis, the elevated production of pro-inflammatory cytokines, such as tumor necrosis factor-α (TNF-α), is crucial." (PMID 41055815, 2025). "Another study showed that the loss of α-gustducin, a key component of taste GPCR signaling, leads to aggravated colitis in mice, with increased levels of tumor necrosis factor (TNF) and gamma interferon (IFN-γ) in the colon." (PMID 40079578, 2025). "Reduced hepatocyte swelling in mice with colitis, inhibited IL-1β and TNF-α expression, and attenuated hepatic inflammation and cholestasis by regulating TLR4 NF-κB and bile acid metabolic pathways." (PMID 40066456, 2025). "Disease-modifying antirheumatic drugs (DMARDs), including methotrexate, sulfasalazine, azathioprine, and anti-TNF-α agents, were prescribed to 4 patients (33.3%) due to ongoing inflammation characterized by osteitis and colitis." (PMID 41357180, 2025). "Studies on colitis have demonstrated that resting peritoneal macrophages from SUCNR1-deficient mice secrete less pro-inflammatory factors IL-1β, IL-6 and TNF-α and, thus, exert a protective effect against colitis." (PMID 40243444, 2025). "Polysaccharides extracted from Ganoderma lucidum and Lentinula edodes demonstrate immunomodulatory effects in colitis models, promoting nitric oxide, tumor necrosis factor-alpha (TNF-α), and interleukin-6 (IL-6) production." (PMID 40427011, 2025). "In DSS-induced colitis, UA lowered IL-6 levels and attenuated inflammatory cell infiltration, while in LPS-induced lung injury, it suppressed TNF-α, IL-1β, and IL-6 production while upregulating anti-inflammatory IL-10 expression." (PMID 40804950, 2025). "Quercetin can also reduce the expression of TNF -α and IL-1β and alleviate the colitis in mice induced by DSS." (PMID 40699713, 2025). "TNF-α expression was markedly elevated in the DSS-induced colitis group relative to the untreated control group, indicating a pronounced inflammatory response." (PMID 40995471, 2025). "We observed that Areg−/− mice exhibited more severe colitis than WT mice, as evidenced by higher intestinal inflammation score and elevated expression levels of inflammatory mediators like IL-1β and TNF-α." (PMID 40247299, 2025). "The strain is further modified to secrete anti‐TNF‐α nanobodies locally, demonstrating superior efficacy over the wild‐type probiotic and infliximab in alleviating murine colitis." (PMID 41017573, 2025).
colitis (continued). "The results revealed a significant increase in the levels of inflammatory cytokines IL-6 and TNF-α in the colon tissue of DSS-induced colitis model mice (p < 0.001) compared with the control group." (PMID 40433374, 2025). "The molecular mechanisms elucidated in this study suggest a multi-faceted approach, wherein Homo suppresses the expression of pro-inflammatory cytokines including, TNF-α, IL-1β, and IL-6, which are critical mediators in the pathogenesis of colitis." (PMID 40529132, 2025). "The UC group showed severe colitis, increased TNF‐α and IL‐6, decreased IL‐10, elevated TOC, reduced TAC, altered VEGF/EGF mRNA, PI3K/AKT activation, and increased apoptosis (Bax/Bcl‐2 ratio, Cytochrome c, Caspase‐9, Caspase‐3)." (PMID 40688608, 2025). "The pre-treatment of A. muciniphila to colitis mice not only stabilized the colon mucosal barrier, regulated inflammatory cytokines (e.g., TNF-α, IL-6) and chemokines MIP-1, but also alleviated dysbiosis of the gut microbiome." (PMID 41488633, 2025). "Like I3C, DIM attenuated the DSS-induced colitis by inhibiting TNF-α, IL-6, IFN-γ, IL-10, iNOS, COX-2, NO, PGE2, myeloperoxidase activity (MPO), and NF-kB." (PMID 40094833, 2025). "Conclusively, this study not only unveils pyruvate as an antagonist of TNFα/NFκB signaling and therapeutic intervention against colitis but also provides mechanistic insight into the mode of action of pyruvate." (PMID 40605975, 2025). "In DSS-induced colitis models, oral administration of PTE not only alleviated colitis symptoms but also significantly reduced TNF-α expression in mice." (PMID 39943187, 2025). "By performing in vivo calcium imaging on DSS-colitis mice at peak disease, we found a reduction in the amplitude of mean TNF and IL-10 responses in the DSS group when compared to controls." (PMID 40268933, 2025). "Therapeutic inhibition of chemerin, such as with cornelian cherry extract, attenuated trinitrobenzene sulfonic acid (TNBS) colitis by reducing TNF-α, IL-17, and chemerin, strengthening epithelial barrier integrity and limiting pathogenic E. coli." (PMID 41301712, 2025). "In a DSS-induced murine colitis model, liraglutide treatment significantly reduced histological inflammation scores (from 7.4 ± 0.3 to 2.2 ± 0.5, p < 0.001), and suppressed TNF-α and IL-6 expression by over 60%." (PMID 40917833, 2025). "Passiflora edulis leaf aqueous extract lowered the pro‐inflammatory cytokines TNF‐a and IL‐1b in a rat model of colitis induced by 2,4,6‐trinitrobenzene sulfonic acid." (PMID 40625630, 2025). "In a DSS-induced colitis mouse study, puerarin markedly reduced colon inflammation by inhibiting the NF-κB pathway—treated mice had significantly lower myeloperoxidase activity and reduced levels of TNF-α, IL-1β, and IL-6 in colonic tissue." (PMID 41008518, 2025). "It has been demonstrated in a model of TNBS-induced colitis that a rise in SOD activity inhibits the production of proinflammatory cytokines TNFα and IL-1β, which are enhancers of ROS production due to the promotion of endosomal internalization of Nox1." (PMID 40305159, 2025). "Our study demonstrated that L. paracasei E10 decreased apoptotic cells and TNF-α levels in the colon tissues of colitis-afflicted mice, while enhancing ZO-1 protein levels in intestinal epithelial cells." (PMID 40724347, 2025). "In our experimental model of colitis, RvD2 treatment consistently led to a significant reduction in the expression of key pro-inflammatory cytokines, including TNFα and IL6, across all tested concentrations (0.01 μM, 0.1 μM, and 0.3 μM)." (PMID 40649782, 2025). "The APS-H-treated colitis mice had down-regulated blood levels of IL-6, TNF-α, and IL-1β, whereas the DSS-treated mice had increased serum levels of these cytokines." (PMID 41010526, 2025).
colitis (continued). "There was a significant difference between the DAI, colon weight-by-length ratio, macroscopic colitis grading, histopathology score, and biomarkers TNF-α and GSH of the SAMe-treated group and the disease-control group." (PMID 40677439, 2025). "Pro-inflammatory cytokines, namely TNF-α, IL-1β, and IL-6, play pivotal roles in the inflammatory process, precipitating tissue damage and exacerbating colitis." (PMID 40077487, 2025). "iTcES treatment resulted in a significant reduction in TNF-α, IL-1β, IL-23, IL-17F, and IL-33 levels; all of these cytokines are known to exacerbate colitis by promoting intestinal epithelial cell death and disrupting the epithelial barrier." (PMID 40576745, 2025). "In this study, TNF-α, IL-1β and IL-6 levels were higher unsupplemented colitis-affected rats compared to healthy rats." (PMID 41515203, 2025). "For example, studies have shown that the transplantation of M2 macrophages can reduce the production of pro-inflammatory cytokines (e.g., IL-6 and TNF-α) in animal models of acute kidney injury and colitis." (PMID 41143725, 2025). "Strains that induced higher levels of the anti-inflammatory cytokine IL-10 and lower levels of pro-inflammatory cytokines such as IL-1β, IL-6, interferon γ (IFNγ), and TNF-α offered protection in induced colitis." (PMID 39767038, 2024). "The same research results confirmed that in the hippocampus of colitis model mice, the TNF and NO concentrations and inducible NOS expression were increased." (PMID 38576620, 2024). "For example, treatment with Bifidobacterium adolescentis IM38 attenuated high fat diet–induced colitis in mice by inhibiting lipopolysaccharide production, NF-κB activation and TNF-expression in colonic epithelial cells." (PMID 38368394, 2024). "Decrease the severity of DSS-induced colitis and the production of pro-inflammatory cytokines such as tumor necrosis factor (TNF)-α, IL-6, and IL-1β." (PMID 39767818, 2024). "In mouse models of colitis, TNF-α-neutralizing nanobodies produced by orally administered Lactococcus lactis or Escherichia coli reduced intestinal inflammation and histopathological markers." (PMID 39062843, 2024). "In conclusion, probiotic VSL#3 is anticipated to be a first-choice medication in managing colitis because it reduces the production of NF-κB and TNF-α in rats with colitis via the TLR4-NF-κB signal pathway." (PMID 39323474, 2024). "The increase of intestinal inflammation in Tlr7-/- mice correlated with an increase in granzyme B+ CD8+ TRM cells, IFN-γ, and TNF-α secretion during DSS colitis and suggest that CD8+ TRM cells contribute to the increased susceptibility seen in Tlr7-/- mice." (PMID 39464882, 2024). "Coumaric acid modulated the expression of inflammatory markers, including NF-κB, TNF-α, iNOS, IL-1β, and IL-6, in the colon during acetic acid-induced colitis." (PMID 38732594, 2024). "On the other hand, Blastocystis ST7 increases the severity of colitis due to increasing the number of harmful bacteria and increasing the number of -T-cells that release inflammatory cytokines such as IL-17 and TNF-α." (PMID 39338600, 2024). "The improvement of colitis after hesperidin treatment is related to the inhibition of pro-inflammatory cytokines TNF-α, IL-6, IL-1β, and IL-33 as well as NF-κB activation in the colon." (PMID 39494333, 2024). "During DSS-induced colitis, proinflammatory macrophages increase, promoting the production of interleukin (IL)-23 and tumor necrosis factor α (TNFα, while anti-inflammatory macrophages, as well as IL-10 induction, decrease." (PMID 38892549, 2024). "Bifidobacterium adolescentis ameliorated DSS-induced colitis by reducing TNF-α, IL-1β, and IL-6 levels and increasing IL-10 and IL-4 levels." (PMID 38540864, 2024). "DSS-induced colitis typically presents as increased colonic epithelial permeability, tight junction (TJ) disruption, and the increased secretion of cytokines such as tumor necrosis factor (TNF)-α, interleukin (IL)-6, IL-1β, and IL-17A." (PMID 38203747, 2024).
colitis (continued). "EPS derived from lactobacillus have been shown to effectively reduce the levels of pro-inflammatory cytokines IL–1ß, IL–6, and TNF–α in colitis mice." (PMID 38731362, 2024). "When colitis mice were administered a probiotic mixture, a significant reduction in TNF-α levels was observed compared to untreated colitis mice." (PMID 39201260, 2024). "TNF-α is secreted in the acute stage of colitis, and IFN-γ is secreted in the chronic stage of colitis." (PMID 38611304, 2024). "Inflammatory cytokines and mediators such as IL-1β, IL-6, and TNF-α are pivotal in initiating and sustaining colitis." (PMID 39061864, 2024). "The concentrations of proinflammatory cytokines IL-6, IL-1β, and TNF-α significantly increased in the serum of mice with colitis induced with DSS, while the concentration of immunoglobulin IgA in serum was decreased in the DSS group." (PMID 38398846, 2024). "Various colitis symptoms in mice, including body weight, thymus index, spleen index, IL-6, TNF-α, IL-1β, IL-10, and IgA, were restored with 100 mg/kg PSPRS and 300 mg/kg PSPRS administration." (PMID 38611336, 2024). "Immunosuppressants, such as tumor necrosis factor (TNF) antagonists, and interleukin blockers, can relieve the symptoms of colitis by blocking inflammatory factors in the body." (PMID 39554349, 2024). "IFX and 1,25-dihydroxyvitamin D3 (VitD3) synergistically prevented the development of colitis by improving clinical signs, pathological and hematological manifestation, and inhibiting intestinal inflammation (decreasing TNF-α, IL-1β, and IL-6)." (PMID 39055880, 2024). "Colonic sections immunostained against TNF-α revealed minimal brown staining in the normal model Group I and positive brown staining in the colitis model Group II." (PMID 39444692, 2024). "Interferon gamma and tumor necrosis factor (TNF) alpha play central roles in the pathogenesis of both ICI colitis and UC." (PMID 39336463, 2024). "Our study also showed a significant increase in colonic expression of interleukin-17A (IL-17A), as well as interferon γ (IFNγ) and tumor necrosis factor α, during colitis in mPGES-1−/− mice compared with that in WT mice." (PMID 39596393, 2024). "H. Cheng and team found that SIN (100 mg/kg and 200 mg/kg) alleviated colitis in mice by reducing TNF-α and interferon-γ (IFN-γ)." (PMID 38276618, 2024). "Mononuclear phagocytes and epithelial cells in the intestine can drive inflammatory cytokines, including IL-1β, TNF-a, and IL-6, which are involved in the occurrence and progression of colitis." (PMID 39458282, 2024). "We first investigated the relationship of miR146a expression to that of pro-inflammatory cytokines IL-6 and TNF in the colons of mice induced with TNBS colitis." (PMID 38786849, 2024). "Bifidobacterium longum CH57 alleviates colitis by inhibiting the NF-κB signaling pathway and TNF-α expression." (PMID 39346650, 2024). "A previous study using a colitis animal model has shown that exercise reduces pro-inflammatory cytokines TNF-α and IL-1β expression, increases anti-inflammatory cytokine IL-10 expression, and reduces stress-induced barrier dysfunction." (PMID 38791116, 2024). "Elevated TNF levels were found in patients with colitis after treatment with ipilimumab and nivolumab." (PMID 39034318, 2024). "In mouse models of colitis, both walnut protein and its enzymatic products effectively suppressed serum IL-1β, IL-6, TNF-α levels, and myeloperoxidase (MPO) activity, thereby preventing colitis progression." (PMID 39203780, 2024). "SE also alleviated LPS-induced myeloperoxidase and TNF-α expression in the colon, resulting in the amelioration of colitis." (PMID 39203872, 2024). "Previously, L. johnsonii N5, which harbors anti-inflammatory-associated genes such as groEL, groES, and folC in its genome, demonstrated a reduction in the expression of pro-inflammatory cytokines including TNF-α in DSS-induced colitis mice." (PMID 39849930, 2024).